RECQL4 (RecQ like helicase 4)
Diseases named in the same sentence as RECQL4 in open-access papers (continued):
Sharing a sentence is not in itself a finding about the gene and the disease.
osteosarcoma (continued). "RecQL4 deficient RTS displays heterogeneous clinical profiles with common features of premature aging and the early development of cancers, in particular osteosarcomas." (PMID 23894508, 2013). ", the next highest incidence of osteosarcoma in humans occurs in a heritable syndrome called Rothmund-Thomson syndrome, which results from homozygosity for RECQL4 helicase ablation." (PMID 21403899, 2011). "The sensitivity of RTS cells to genotoxic agents exploiting cells with a known RECQL4 status is being elucidated and is aimed at optimizing the chemotherapeutic regimen for osteosarcoma." (PMID 20113479, 2010). "Interestingly, increased RECQL4 expression has been reported in some cases of sporadic osteosarcoma." (PMID 39870799, 2025). "The predominant subset of RECQL4-mutated patients represents RTS type-II or Thomson-like entity, characterized by poikiloderma, skeletal defects and cancer predisposition (osteosarcoma (OS) and less frequently squamous cell carcinoma of the skin, hematological tumors and other malignancies)." (PMID 29642415, 2018). "We propose that tumor suppression and osteosarcoma susceptibility are most likely a function of mutant, not null, alleles of RECQL4." (PMID 25859855, 2015). "Furthermore, overexpression of the RECQL4 gene with chromosomal aberrations and instability in osteosarcoma has also been reported." (PMID 24944681, 2014). "However, increased copy number and increased protein expression of RECQL4 have been reported as a frequent event in sporadic osteosarcoma." (PMID 22685381, 2012). "Interestingly, in osteosarcoma, chromosomal rearrangements and genomic imbalances affecting 8q24 in which the RECQL4 gene maps are frequent and the increased expression of RecQL4 are correlated to some type of chromosome instability." (PMID 21698130, 2011). "RECQL4 is a gene whose protein product is involved in repair of DNA double stranded breaks and deregulation of its expression was recently shown to be strongly correlated with genomic instability in osteosarcoma." (PMID 20465837, 2010). "Finally, a DNA repair gene, RECQL4, has been shown to be overexpressed, and its level of overexpression correlates with overall genomic instability in osteosarcoma." (PMID 20465837, 2010). "Genotype-phenotype analysis shows that RTS patients with RECQL4 mutations are at a significantly higher risk of developing osteosarcoma as compared to RTS patients without RECQL4 mutations." (PMID 20113479, 2010). "The role of RECQL4 in normal bone development and osteosarcoma formation is largely unknown." (PMID 25859855, 2015). "Somatic mutations of RECQL4 have not been detected in sporadic osteosarcomas, but the present study raises the possibility that genetic amplification may be the method by which RECQL4 dysfunction presents in sporadic tumors." (PMID 24835790, 2014). "Because RECQL4 helicase has not been found to be mutated or deleted in sporadic human osteosarcomas, it is felt that its disruption represents more of a route to generate genomic instability generally than the silencing of a specific tumor suppressor important to osteosarcomagenesis." (PMID 21403899, 2011). "RecQL4-mediated regulation of AURKB expression was next investigated in RecQL4-silenced hTERT-immortalized (HMEC-hT1) and malignantly transformed osteosarcoma cells (U2OS)." (PMID 30206236, 2018).
osteosarcoma (continued). "As a first step to determine whether RECQL4 is required for DNA replication, we monitored the cell cycle profile of U2OS osteosarcoma cells after depleting RECQL4 by siRNA." (PMID 38565932, 2024). "In contrast to Type 1 RTS patients, who have no elevation in risk of osteosarcoma, Type 2 RTS patients with biallelic RECQL4 pathogenic variants have a significantly elevated lifetime risk of osteosarcoma." (PMID 34965247, 2021). "A model of Recql4 helicase disruption has been generated in the mouse by gene targeting, but osteosarcomas have not been identified, despite recapitulation of other features of the autosomal recessive heritable disorder." (PMID 21403899, 2011). "Additionally, RECQL4 expression significantly correlates with its downstream target, MAFB, a transcription factor whose inhibition affects aggressiveness of ovarian cancer cells as well as osteosarcoma stem cells." (PMID 35782872, 2022). "Interestingly, the animals with no Recql4 in bone cells did not develop osteosarcoma." (PMID 25859855, 2015).
breast carcinoma (34 papers, 2012 to 2025). "Recent studies also reported that germline deleterious mutations in RECQL4 are associated with predisposition to breast cancer and prostate cancer." (PMID 38509102, 2024). "Mutations in RECQL4 increase the risk of developing breast cancer, and two intronic SNPs in RECQL4 were associated with outcomes of glioblastoma patients." (PMID 33050631, 2020). "Genomic alterations, high RECQL4 mRNA or protein expression were associated with aggressive behaviour in breast cancers and poor survival." (PMID 33050631, 2020). "More specifically, RecQL4-survivin pathway provides a potential target for the development of new diagnostic and treatment modalities for breast cancer patients." (PMID 23894508, 2013). "An absolute lack of tumor growth in 4 of 7 mice injected with RecQL4-suppressed breast cancer cells strongly suggests that RecQL4 expression is intrinsically associated with breast cancer cell growth and tumor progression." (PMID 23894508, 2013). "Interestingly, we observed that the presence of RECQL4 high amplification was associated with reduced OS in melanoma, breast cancer and prostate cancer." (PMID 39812592, 2025). "Thus, their study confirmed that RECQL4 upregulation is linked with tumor progression in breast cancers." (PMID 36552262, 2022). "Notably, the chromosomal site of the RECQL4 gene is considered as a hot-spot position for frequent mutation often highly detected in sporadic breast cancers." (PMID 36552262, 2022). "Germline mutations in RECQL4 can cause the Rothmund–Thomson syndrome and sporadic breast cancer." (PMID 33889545, 2021). "RECQL4 copy number alterations correlated with specific cancer types, including prostate, ovarian, non-small cell lung, melanoma, colorectal, and breast cancer." (PMID 40196015, 2025). "RECQL4 locates at the common amplification site in sporadic breast cancer and plays a carcinogenic role in breast tumorigenesis." (PMID 39095659, 2024). "In our study, these ARGs were all statistically significant in gene expression between breast cancer and normal tissues, and all had amplification mutations in BC, with PTK2 and RECQL4 being the most prominent." (PMID 36323529, 2023). "Several tumor types where RECQL4 is over-expressed are treated with cisplatin, including breast cancer." (PMID 36126066, 2022). "Similar to prostate cancer cells, breast cancer cells show overexpression of RECQL4 A study demonstrated that the majority of the breast cancer cells exhibited gene amplification via increased 8q24." (PMID 35782872, 2022). "In vitro studies comparing multiple breast cancer cell lines have also found high mRNA levels of RECQL4 in the cancer lines." (PMID 35267530, 2022). "Studies reported that RECQL4 is not only a metastasis-promoting gene but also a prognostic indicator in breast cancer, as elevated levels of RECQL4 gene amplification, mRNA, and protein demonstrated considerably increased tumor aggressiveness." (PMID 35782872, 2022). "For instance, the subcellular localization of RECQL4 in normal breast tissue is exclusively in the nucleus while breast cancer tissues had complex subcellular localization." (PMID 35267530, 2022). "It has been reported that 88.4% (38/43) of breast cancer tissues displayed a three-fold increase in mRNA expression of RECQL4 compared to normal tissues." (PMID 35267530, 2022). "A previous study has reported that RECQL4’s CNV are associated with its overexpression and increased breast cancer aggressiveness." (PMID 36060256, 2022). "This association between overexpression and cancer progression highlights the potential clinical benefit of targeting RECQL4 in breast cancer." (PMID 35782872, 2022). "A considerable body of evidence indicates that RECQL4 is elevated in a large number of malignant tumors, such as ovarian cancer, gastric cancer and breast cancer." (PMID 34486474, 2021).
breast carcinoma (continued). "A growing body of literature has shown that RECQL4 is highly expressed in various malignant tumors, such as ovarian cancer, gastric cancer and breast cancer." (PMID 34486474, 2021). "In contrast, elevated expression of RECQL4 is observed in prostate cancer, breast cancer, and hepatocellular carcinoma." (PMID 33014878, 2020). "RECQL4 depletion impaired DNA replication and increased chemosensitivity in cultured breast cancer cells." (PMID 33050631, 2020). "A high RECQL4 gene expression level has recently been reported to confer proliferation advantage and survival to breast cancer cells." (PMID 24416132, 2014). "Further, RecQL4 suppression in breast cancer cells reduced the expression of survivin after oxidative DNA damage." (PMID 23894508, 2013). "In this study, we have demonstrated that shRNA-mediated RecQL4 suppression in breast cancer cells not only inhibits their in vitro clonogenic survival and in vivo tumorigenicity, but also sensitizes them to apoptotic induction." (PMID 23894508, 2013). "Although the precise mode of survivin regulation by RecQL4 awaits further studies, our finding suggests that RecQL4 probable protects the breast cancer cells from DNA damage-induced apoptosis through upregulation of survivin." (PMID 23894508, 2013). "Suppression of RecQL4 not only affected the proliferation but also abolished the tumorigenic potential of breast cancer cells." (PMID 23894508, 2013). "In the light of these observations, there is a strong possibility that RecQL4 through its elevated expression contributes to infinite replicative potential of breast cancer cells." (PMID 23894508, 2013). "In this study, we have demonstrated that RecQL4 elevated expression confers proliferation advantage and survival to breast cancer cells." (PMID 23894508, 2013). "In corroboration with our earlier results, RecQL4 protein was substantially elevated in all the breast cancer cell lines with the exception of MDA-MB231 relative to primary HMEC cells." (PMID 23894508, 2013). "The highest level of RecQL4 expression observed in metastatic prostate and breast cancer cells points out a potential prognostic significance of RecQL4 for advanced stages of breast and prostate cancers." (PMID 23894508, 2013). "Suppression of RecQL4 by shRNA dramatically increased the apoptotic potential of breast cancer cells." (PMID 23894508, 2013). "88.4% (38/43) of breast cancer tissues displayed a three-fold higher expression in RecQL4 mRNA than normal tissue samples." (PMID 23894508, 2013). "Consistent with over representation of 8q24, a significantly elevated expression of RecQL4 was observed in most of the breast cancer cell lines." (PMID 23894508, 2013). "These novel properties make RecQL4 as an ideal targeting molecule for improving the efficiency of breast cancer treatment." (PMID 23894508, 2013). "shRNA-mediated RecQL4 suppression in MDA-MB453 breast cancer cells not only significantly inhibit the in vitro clonogenic survival and in vivo tumorigenicity." (PMID 23894508, 2013). "The three DSB repair genes, BLM, RECQL4 and DCLRE1C, disrupted in the case group all represent attractive breast cancer susceptibility genes." (PMID 22737080, 2012). "The highest frequency of RECQL4 amplification was detected in ovarian cancer (10.14%; 120 of 1183 cases), melanoma (6.04%; 69 of 1142 cases), breast cancer (5.98%; 156 of 2609 cases), prostate cancer (3.68%; 80 of 2172 cases) and colorectal cancer (3.52%; 125 of 3548 cases)." (PMID 39812592, 2025). "Recently, RECQL4 has been suggested to be involved in breast cancer." (PMID 35267530, 2022).
breast carcinoma (continued). "When compared to ER+ breast cancers, ER- breast cancers have elevated levels of RECQL4 expression." (PMID 36126066, 2022). "The highest RECQL4 expression was observed in stage IV breast cancer." (PMID 35267530, 2022). "Moreover, there have been reported direct interactions of E2F1 and retinoblastoma protein (RB) with the promoter of RECQL4 in prostate cancer cells and RECQL4 with BIRC5 in breast cancer cells." (PMID 33541355, 2021). "However, recent studies have shown that RECQL4 acts as a tumor-promotor in some cancers, such as prostate cancer, colorectal cancer, and breast cancer." (PMID 31248416, 2019). "The candidate oncogene RECQL4, which might be involved in endocrine resistance, could be also a potential therapeutic target as recently shown in breast cancer cells." (PMID 24416132, 2014). "In addition to proliferation inhibition, RecQL4 suppression also greatly reduced the tumorigenic potential of breast cancer cells in vivo." (PMID 23894508, 2013). "Elevated level of RecQL4 observed in human breast cancer cells and tissues prompted us to verify whether RecQL4 is crucial for breast cancer cell survival and tumorigenesis." (PMID 23894508, 2013). "Additionally, RecQL4 through its interaction with survivin seems to be a key factor for determining the fate of breast cancer cells after DNA damage." (PMID 23894508, 2013). "Since over representation of RecQL4 harboring locus 8q24 is frequently observed in breast cancer cells, we hypothesized that RecQL4 plays critical roles in breast carcinogenesis." (PMID 23894508, 2013). "Our study suggests that RecQL4 probably regulates the survival of breast cancer cells through its interaction with survivin, and RecQL4 targeting may prove to be effective strategy for breast cancer treatment." (PMID 23894508, 2013). "To investigate the mechanistic basis of the three-gene prognostic signature (EGR3, RECQL4, MMP1) in breast cancer progression, we performed differential expression analysis followed by GO and KEGG pathway enrichment analyses between the two molecular subtypes." (PMID 41472745, 2025). "This study establishes a machine learning-optimized 3-gene prognostic signature (EGR3, RECQL4, MMP1) that bridges prognostic stratification and tumor-immune interplay in breast cancer, offering both clinical and mechanistic advancements." (PMID 41472745, 2025). "To elucidate the functional roles of the three prognostic signature genes (EGR3, RECQL4, and MMP1) in breast cancer pathogenesis, we conducted comprehensive multi-omics analyses across multiple datasets." (PMID 41472745, 2025). "For some genes, single P/LP variants were detected either only in the group of patients with breast cancer (APC, MDM1, MRE11, POLD1, NF1, RAD51C, RECQL4, and WRN) or only in the control group (MCPH1, MSH3, and XPC)." (PMID 39684352, 2024). "Six breast cancer differentially localized proteins were got: CCNT1, NSUN5, PRPF4, RECQL4, UTP6, ZNF500." (PMID 39095659, 2024). "Based on the results of survival analysis (p < 0.05), it was found that the results of UTP6, NSUN5 and RECQL4 proteins were more relevant to the prognosis of breast cancer, while the results of CCNT1 and PRPF4 were not." (PMID 39095659, 2024). "Based on their biological functions BLM, RECQL4 and DCLRE1C all represent attractive susceptibility genes, although to date clearly deleterious, breast cancer related mutations have not been reported in any of them." (PMID 22737080, 2012).
Werner syndrome (34 papers, 2007 to 2025). "Mutations in WRN, BLM, and RECQL4 cause Werner syndrome (WS), Bloom syndrome (BS), and Rothmund–Thomson syndrome (RTS), respectively, which are associated with premature aging, cancer predisposition, and chromosome abnormalities." (PMID 35681785, 2022). "Mutations in WRN, BLM, and RecQL4 cause Werner syndrome (WS), Bloom syndrome (BS), and Rothmud-Thomson syndrome (RTS), respectively, which are associated with premature aging, cancer predisposition, and chromosome abnormalities." (PMID 33266355, 2020). "Inactivation of RecQL2 (WRN), RecQL3 (BLM), and RecQL4 leads to Werner’s syndrome, Bloom syndrome and Rothmund–Thomson syndrome, respectively; these disorders are characterized by genome instability, increased cancer risk and, in the case of Werner syndrome, adult-onset premature aging." (PMID 32085395, 2020). "Interestingly, other key members of the same protein family have been associated with well-known recessive cancer predisposition syndromes (BLM, Bloom syndrome; RECQL4, Rothmund–Thompson syndrome; WRN, Werner syndrome)." (PMID 30871259, 2019). "Several syndromes are associated to the RecQ genes’ family including Werner syndrome (WS), Bloom syndrome (BS) and Rothmund Thomson syndrome (RTS), that are respectively associated with pathogenic variants in RECQL2/WRN, RECQL3/BLM, and RECQL4 genes." (PMID 31829210, 2019). "Members have key roles in maintaining genomic stability, with inactivation leading to cancer predisposition syndromes including Bloom’s syndrome (BLM), Werner syndrome (WRN), and in the case of RecQL4, three syndromes: Rothmund–Thomson syndrome (RTS), Baller–Gerold syndrome (BGS) and RAPADILINO." (PMID 29757235, 2018). "In human cells, the RecQ helicase family comprises five DNA helicases: RECQL1 (also known as RECQL or RECQ1), Bloom syndrome (BLM), Werner syndrome (WRN), Rothmund–Thomson syndrome (RTS; also known as RECQL4) and RECQL5." (PMID 25620975, 2014).
Bloom syndrome (33 papers, 2007 to 2025). Bloom syndrome (BSyn) is a rare chromosomal breakage syndrome characterized by a marked genetic instability associated with pre- and postnatal growth retardation, facial sun-sensitive telangiectatic erythema, increased susceptibility to infections, and predisposition to cancer. "WRN is a member of the RecQ helicase gene family, and other members of the family include BLM and RTS/RECQL4, which are mutated in Bloom syndrome (BS) and Rothmund–Thomson syndrome (RTS), respectively." (PMID 25688260, 2015).